IGFBP3 (insulin like growth factor binding protein 3)
Diseases named in the same sentence as IGFBP3 in open-access papers (continued):
Sharing a sentence is not in itself a finding about the gene and the disease.
asthma (15 papers, 2013 to 2026). "We identified IGFBP-3 as a direct target of miR-34/449 and showed that inflammatory responses and airway fibrosis associated with asthma may be mediated by the modulation of IGFBP-3 and its effects on the regulation of autophagy." (PMID 28796252, 2017). "Studies investigating the targets of these miRNAs revealed differential expression of IGFBP-3 between asthma patients and healthy individuals, further supporting the involvement of IGF signaling in disease pathogenesis." (PMID 41156032, 2025). "A study of seven genes regulated by these miRNAs revealed differential expression of IGFBP3 between asthma patients and healthy individuals." (PMID 37511378, 2023). "In mice, IGF1 mediates allergic airway inflammation, and IGFBP3 was shown to block the effects of asthma." (PMID 34440118, 2021). "In particular, increased expression of Igfbp3 in the NVP 2 weeks group corresponds with its protective role in asthma." (PMID 34440118, 2021). "IGFBP-3 inactivates NF-κB signaling pathway in asthma in that it degrades IκBa and p65-NF-κB through IGFBP-3 receptor-mediated, IGF-1-independent activation of caspases, which further blocks TNF-α-induced inflammation and eosinophil migration." (PMID 30018981, 2018). "As has been reviewed, IGF-1 signaling pathway and IGFBP-3 are of therapeutic significance in asthma." (PMID 30018981, 2018). "Regarding increased Igfbp3 and Igfbp5 levels in HDM-treated Igf1r-deficient mice, exogenous IGFBP3 and IGFBP5 administration blocks the physiological consequences of asthma and enhances epithelial cell adhesion to maintain the epithelial-mesenchymal boundary." (PMID 29272313, 2017). "Regarding asthma, further studies and clinical trials are needed to evaluate the efficacy of add-on therapy with lichochalcone A, bevacizumab, diosmetin, epigallocatechin gallate, IGFBP-3, Neovastat, endostatin, PEDF, and melatonin." (PMID 37174726, 2023). "Considering this, the creation of an IGFBP-3 antagonist could be a promise therapeutic target for asthma treatment." (PMID 24151607, 2013). "Some of the disease states that show IGF-independent actions of IGFBP-3 include cancer and asthma." (PMID 23383064, 2013). "IGFBP-3 suppresses VEGF production by both IGF-1-dependent and hypoxia-inducible factor- (HIF-) dependent mechanisms, while VEGF has been shown to be associated with subepithelial fibrosis by regulation of TGF-β1 expression through the PI3K/AKT signaling pathway in asthma." (PMID 30018981, 2018). "In obese asthma patients, we found higher hsa-miR-26a-1-3p and IGF-1R values and lower values for hsa-miR-376a-3p and IGFBP-3." (PMID 37511378, 2023). "We identified lichochalcone A, bevacizumab, azithromycin (AZT), vitamin D, diosmetin, epigallocatechin gallate, IGFBP-3, Neovastat (AE-941), endostatin, PEDF, and melatonin as putative add-on drugs in asthma with anti-VEGF properties." (PMID 37174726, 2023). "In disagreement with the previous studies, IGFBP3, the putative ligand of TM219 protein, is upregulated after allergen challenge in asthma animal model and in patients with asthma." (PMID 31220095, 2019). "The expression of IGFBP-3 is high in asthmatic airway epithelial cells in situ and is increased in BALF of patients with asthma after allergen challenge." (PMID 30018981, 2018). "The levels of inflammatory factors (IL-5, IL-6, IL-13, and TNF-α) and those of fibrosis-related proteins (basic fibroblast growth factor (bFGF), IGFBP-3, and TGF-β) were significantly higher in asthma patients than in healthy controls." (PMID 28796252, 2017). "Although little is known about the role of IGFs in human asthma, IGF1 and IGFBP3 were suggested to be involved in allergic airway inflammation and remodeling." (PMID 29272313, 2017). "Interestingly, in obese asthma patients, elevated levels of miR-26a-1-3p and IGF-1R were observed, while miR-376a-3p and IGFBP-3 levels were decreased." (PMID 41156032, 2025).
asthma (continued). "A negative correlation was found between GH, IGF-1, and IGFBP3 levels and asthma severity (p < 0.05)." (PMID 38754227, 2024). "Administration of insulin-like growth factor (IGF) binding protein, specifically IGFBP-3, reduced HIF-1α/HIF-2α signaling, which mediates VEGF expression, and IGF-I production, contributing to reduced VEGF expression, airway inflammation, and bronchial hyperreactivity." (PMID 37174726, 2023).
cervical carcinoma (15 papers, 2008 to 2025). A carcinoma arising from either the exocervical squamous epithelium or the endocervical glandular epithelium. "A reduced expression of IGFBP-3 mRNA level appears to be associated with progression to cervical cancer." (PMID 40878909, 2025). "Conversely, FASN promotes lymphangiogenesis and metastasis in cervical cancer via the secretion of PDGF-AA/IGFBP3." (PMID 40641601, 2025). "In cervical cancer, IGFBP3 inhibits tumor angiogenesis by intracellular regulation of THBS1 expression." (PMID 35966888, 2022). "It has previously been shown that high-level expression of IGFBP3 stimulated growth inhibition of tumors in an HPV16 E7-induced cervical cancer model." (PMID 32849815, 2020). "On the other hand, low levels of IGFBP-3 and IGF-1R mRNA in cervical scrapes were found to be associated with progression to cervical cancer." (PMID 25333772, 2014). "This study aims to investigate the association of IGF-1 system and clinical outcome of cervical cancer, by analysing the serum levels of IGF-1 and IGFBP-3, and tissue abundances of IGF-1R for the same patient." (PMID 18781172, 2008). "This positive regulatory circuit formed by KCNMB2-AS1 and IGFBP3 significantly induced cervical cancer progression and targeting KCNMB2-AS1 and its related molecules may be a potential detective and therapeutic way for cervical cancer patients." (PMID 37069649, 2023). "One study inferred that the IGFBP-3 level could be used in predicting prognosis of cervical cancer, but the study result should be limited because of small sample size and concealed stage." (PMID 18781172, 2008). "In the past, DNMT3a has been shown to epigenetically regulate the levels of IGFBP3 in cervical cancer by CUL4B;15 DNMT3a deprivation in liver cancer results in an increased IGFBP3 expression." (PMID 28393842, 2017). "On the other hand, the results from another study of preoperative serum total IGF-1 or IGFBP-3 levels failed to predict cervical cancer mortality and recurrence." (PMID 25333772, 2014). "As it is generally assumed that elevated IGFBP-3 level has a protective function in cancer, it was reported that serum levels of IGFBP-3 in patients with cervical cancer are significantly lower than levels in controls, and they revert to normal following therapy." (PMID 25333772, 2014). "Results showed that median protein levels of IGF-2 were significantly lower in cervical cancer cases vs. controls and significantly higher values of IGFBP-3 were found in HSIL vs. controls, and were not affected by HR-HPV infection." (PMID 25333772, 2014). "(ii) Preoperative serum total IGF-1 or IGFBP-3 levels failed to predict cervical cancer death and recurrence." (PMID 18781172, 2008). "This was also established in a modified organotypic raft culture containing the HPV16 positive cervical cancer cell line, Caski, where IGFBP2, but not IGFBP3, significantly inhibited invasion of the epithelial cells." (PMID 26107517, 2015). "(iii) The colocalisation of IGF-1 and IGF-1R in the cancerous tissues, and the lack of correlation between circulating IGF-1 or IGFBP-3, and IGF-1R overexpression in cervical cancer cells suggest likely autocrine or paracrine IGF-1 stimulation of IGF-1R signalling." (PMID 18781172, 2008). "Moreover, the serum level of IGF-1 or IGFBP-3 did not statistically differ between the two distinct IGF-1R overexpressions (P=0.77 and P=0.07, respectively), indicating no direct correlation between circulating IGF-1 or IGFBP-3, and IGF-1R overexpression in cervical cancer cells." (PMID 18781172, 2008).
Ewing sarcoma (15 papers, 2011 to 2025). A small round cell tumor that lacks morphologic, immunohistochemical, and electron microscopic evidence of neuroectodermal differentiation. "EWS-FLI1 fusion protein, the hallmark of Ewing's sarcoma, downregulates insulin-like growth factor binding protein 3, IGFBP3, and upregulates IGF-1 expression resulting in enhanced IGF1R." (PMID 21494688, 2011). "In summary, our data suggested that IGF-1R, IGF-1, IGFBP-1, and IGFBP-3 levels are associated with bone tumor malignancy, metastasis, and recurrence that might serve as biomarkers for osteosarcoma and Ewing sarcoma recurrence." (PMID 36713521, 2022). "In a study on Ewing sarcoma, high levels of both circulating IGF-1 and IGFBP-3 in the serum were associated with improved OS in patients treated with chemotherapy." (PMID 37510722, 2023). "The circulating level of IGF-1, IGFPB-1, and IGFBP-3 were increased in osteosarcoma and Ewing sarcoma and GCT groups that were correlated significantly to the tumor severity." (PMID 36713521, 2022). "Forced expression of IGFBP-3 in TC-71 Ewing sarcoma cells induced decreased production and/or activity of matrix metalloprotease-9 (MMP-9) and vascular endothelial factor (VEGF)-A, that abolished EWS metastatic ability." (PMID 34069554, 2021). "It is known that EWS-FLI1 protein, which is characteristic for Ewing's sarcoma, binds the promoter of insulin-like growth factor binding protein 3 (IGFBP3) to suppress the expression of IGFBP3, which sequesters circulating IGF1." (PMID 32317857, 2020). "In Ewing sarcoma, IGF binding protein 3 (IGFBP3) is downregulated by the EWSR1-FLI1 fusion gene, activating the IGF pathway." (PMID 27418340, 2016). "In support of this claim, a mechanism has been proposed linking the translocation associated with Ewings sarcoma with the IGF binding protein 3 (IGFBP3) promoter, reducing IGFBP3 production and effectively up-regulating IFG1." (PMID 23226201, 2012). "IGFBP-3 expression is generally inhibited in Ewing's sarcoma cells, as a consequence of EWS/FLI1 expression." (PMID 21197468, 2011). "Of note, IGFBP3 is also up-regulated in Ewing sarcoma cells after suppression of the EWS::FLI1 fusion, indicating that it may be a more common downstream effector of oncogenic transcription factors in mesenchymal malignancies." (PMID 40901948, 2025). "However, between different Ewing sarcoma subtypes, only patients with high-grade tumor (3.93 ± 0.13) expressed a significant elevated level of IGFBP-3 compared to patients with low-grade tumor (3.24 ± 0.17) (P=0.005)." (PMID 36713521, 2022). "Chromosomal rearrangements leading to oncogenic fusion like TMPRSS2-ERG, EWS-WT1, and PAX3-FKHR, sustain IGF1R expression in prostate cancer, desmoplastic small cell tumor and alveolar rhabdomyosarcoma, respectively, while EWS-FLI favors IGF1 but inhibits IGFBP3 transcription in Ewing sarcoma." (PMID 34440844, 2021). "In Ewing sarcoma cell lines EWS/FLI1 suppresses expression of IGFBP3, but the transcriptional activity of the wildtype transcription factor FLI1 in SPN may differ." (PMID 27539223, 2016). "Also, it was illustrated that exogenous IGFBP3 reduced Ewing sarcoma motility and growth." (PMID 36713521, 2022). "Exposure of neoplastic cells to IGFBP-3 inhibits their growth, migratory, invasive, angiogenic, and metastatic potential, therefore demonstrating the protein as a molecule of therapeutic relevance to be considered in the treatment of patients with Ewing sarcoma." (PMID 21197468, 2011). "Examining the IGF-1 family revealed an increase in the gene and protein level of IGF-1R in bone tumors of osteosarcoma and Ewing sarcoma compared to tumor margins as well as the circulating level of IGF-1, IGFBP-, and IGFBP-3 in these patients." (PMID 36713521, 2022). "EWS-FLI1 represses the transcription of IGFBP3, while favoring the transcription of IGF1, which is a critical step in Ewing sarcoma tumorigenesis." (PMID 34440844, 2021).
Ewing sarcoma (continued). "The IGF-1 pathway is functionally important for the pathogenesis and progression of Ewing Sarcoma and the fusion protein EWS/FLI1 has been shown to downregulate the expression of IGFBP3 in Ewing sarcoma cell lines." (PMID 27539223, 2016). "IGFBP3 was highly downregulated in three out of four analyses, and has been shown to elicit anticancer effects by inhibiting IGF1R signaling in Ewing sarcoma." (PMID 23688189, 2013). "Next, expression levels of eight EWS-FLI1 associated target genes (GLI1, NEX2.2, CyclinD, c-MYC, NR01B, IGF1R, EZH2, and CD99) which were known to be upregulated, and three genes (FOXO1, IGFBP3, and LOX) known to be down regulated in Ewing’s sarcoma was assessed." (PMID 28775288, 2017). "The expression of the selected target genes in Ewing’s sarcoma (CAV1, NR0B1, IGFBP3 and TGFBR2), together with the expression of HIST1H4L, KCNN2, ECRG4 and LDOC1, was then validated in an independent series of PCa with and without ETS gene fusions, as well as in a series of ESFT and ARMS." (PMID 23185447, 2012).
Alzheimer disease (14 papers, 2014 to 2024). A progressive, neurodegenerative disease characterized by loss of function and death of nerve cells in several areas of the brain leading to loss of cognitive function such as memory and language. "Prior findings also emphasized on the role of IGFBP-3 in neuronal degeneration by elevation of IGFBP-3 activity in the brains of patients with Alzheimer’s disease." (PMID 38630771, 2024). "In vitro studies have demonstrated that humanin functions against Alzheimer disease related insults to the cell, moreover, IGFBP-3 has been demonstrated to be increased in Alzheimer’s disease." (PMID 32478064, 2020). "A recent study of human Alzheimers patients has identified an increase in astrocyte production of IGF binding protein 3 (IGFBP3) as a contributory factor to Alzheimers disease pathology." (PMID 28238777, 2017). "IGFBP3, which is the main binding target of IGF-1, plays an important role in regulating the activity and transport of IGF-1, and was reported to be independently associated with AF in the elderly population in the System-IGF-1 Pathway and Alzheimer’s Disease Clinical Trial (SIGAL)." (PMID 35911532, 2022). "VRF from gG-expressing cells contains less insulin-like growth factor binding protein 3 (IGFBP3), a protein that induces phosphorylation of tau, potentially playing a role in Alzheimer’s disease." (PMID 38275838, 2024).
breast tumor (14 papers, 2005 to 2024). "In wild-type mice, tumor IGFBP-3 gene expression was positively associated with tumor weight, consistent with some clinical studies showing that high IGFBP-3 abundance in breast tumor tissue is associated with high tumor grade and poor prognosis." (PMID 29623068, 2018). "In the breast tumor microenvironment, it has been reported that GRP78 also promotes autophagy by binding to insulin-like growth factor binding protein-3 (IGFBP-3), which is associated with poor prognosis." (PMID 37190065, 2023). "A detailed analysis of IGFBP-3 expression within breast tumors uncovered that IGFBP-3 is highly expressed in stromal tissue within the tumor, but its expression is suppressed within the malignant epithelial cells." (PMID 31693710, 2019). "The role of IGFBP-3 expression in breast tumors should therefore be understood in the context of complex regulation for cancer cell growth." (PMID 17210081, 2007). "This is further supported by four clinical studies of breast tumours, including the present study demonstrating a spectrum of increased IGFBP-3 levels, with the highest expression indicative of a more malignant phenotype." (PMID 15642160, 2005). "There have been very few observations of nuclear localisation of IGFBPs in vivo, with cytoplasmic IGFBP-5 expression in breast tumours and, similarly, cytoplasmic IGFBP-3 in normal colonic crypts[B6,9]." (PMID 15642160, 2005). "IGFBP3 can promote breast tumor growth by regulating tumor immune microenvironment." (PMID 37088808, 2023). "Increasing IGFBP-3 levels in breast tumours may indicate adverse prognostic cancers, with contradictory implications on patient outcomes[B24,25] to reflect the complexity of IGFBP-3 effects on cell proliferation[B27,28,30]." (PMID 15642160, 2005). "We found a significant (p < 0.003) trend towards poorer overall survival for patients with breast tumours with low GRP78 and high IGFBP-3 mRNA." (PMID 33352865, 2020). "IGF1 was expressed in 30% of breast tumors, IGF1R in 26%, IGFBP2 in 74%, and IGFBP3 in 32%." (PMID 25619494, 2015). "This is also seen in breast tumor tissue where many, though not all, studies have shown that expression of IGFBP-3 mRNA and protein is higher in ER-negative tumors compared to ER-positive tumors." (PMID 26221601, 2015). "Our results indicating that the function of IGFBP-3 is either pro- or anti-tumorigenic depending on levels of GRP78, suggest that the key to improving the clinical outcome of patients is to implement measurement of both markers in breast tumours in clinical practice." (PMID 33352865, 2020). "Consistent with this, an assessment of IGFBP-3 mRNA levels in GRP78 mRNA negative cases from METABRIC database also revealed a trend towards poorer overall survival and disease-free survival in breast tumours with low GRP78 and high IGFBP-3 mRNA." (PMID 33352865, 2020).